AIM2 (absent in melanoma 2)
Diseases named in the same sentence as AIM2 in open-access papers (continued):
Sharing a sentence is not in itself a finding about the gene and the disease.
infection (continued). "possess the ability to initiate canonical inflammasomes, specifically targeting the PYD, NACHT, and LRR domains containing protein 3 (NLRP3) and absent in melanoma 2 (AIM2) inflammasomes, typically within a short period following infection." (PMID 39065071, 2024). "As a consequence, we interrogated if mAdV3 is generally able to modify host inflammasome responses by individually activating NLRP3 (by nigericin treatment), AIM2 (by poly-dAdT transfection) and PYRIN (by treatment with UCN-01) and NLRC4 (infection with SPI-1 induced Salmonella)." (PMID 39366977, 2024). "It was also suggested that in response to the infection of specific pathogens such as HSV and Francisella, AIM2 inflammasome assembly can lead to PANoptosis, which is characterized by the concomitant activation of pyroptosis, apoptosis, and necroptosis, as a protection mechanism for the host." (PMID 37817895, 2023). "Assembly and activation of the AIM2 inflammasome is identified in infections by RNA viruses such as SARS-CoV-2 and IAV but not other types of dsDNA viruses." (PMID 37515138, 2023). "The inflammasome molecules AIM2, NLRP3, NLRP6 and NLR Family Apoptosis Inhibitory Protein (NAIP)/NLRC4 were reported to play important roles in epithelial cells by protecting against infection and maintaining tissue homoeostasis." (PMID 37365163, 2023). "For example, Absent in melanoma 2 (AIM2), which is part of one of the inflammasome complexes and DNA sensor for Lm, was altered only in WT BMDCs upon infection." (PMID 36131943, 2022). "This suggests that NLRC4—but not NLRP3, Caspase-11 or AIM2—efficiently promotes neutrophil pyroptosis upon infection with P. aeruginosa pyroptotic strains." (PMID 35849616, 2022). "This is not surprising since AIM2 recognizes any type of dsDNA but interesting because Mtb does not activate the AIM2 inflammasome upon infection of BMDCs or BMDMs." (PMID 35237260, 2022). "Likewise, Ifi202b has been shown to be upregulated upon L. major footpad infection in C57BL/6 mice and its corresponding P202 protein to exert an inhibitory effect on the AIM2 inflammasome." (PMID 35992159, 2022). "Importantly, we found that WT, Gbp1–/–, Gbp2–/–, Gbp3–/–, Gbp5–/–, and Aim2–/– BMDMs all released similar levels of IL-1β, IL-18 and LDH in response to infection with F. novicida in the presence of E. coli LPS." (PMID 35906252, 2022). "We found that WT BMDMs produced IFN-β in response to HSV1 (MOI, 10; 6 h post-infection) or F. novicida infection (MOI, 1; 3 h post-infection), while Aim2–/–, Asc–/– and Casp1–/– BMDMs did not." (PMID 34471287, 2021). "In Plasmodium berghei and Aspergillus fumigatus, AIM2 and NLRP3 may function in a redundant manner to trigger inflammasome activation and, consequently, aid in pathogen infection control." (PMID 33897690, 2021). "Aim2 is a dsDNA sensor that upon recognition induces the formation of an inflammasome complex releasing IL1β and IL18 from the cell as a defense mechanism to control infection." (PMID 34047695, 2021). "In previous studies, immunocompetent WT mice and mice lacking the inflammasome components like NLRP3 or absent in melanoma 2(AIM2) do not succumb to infection with A. fumigatus." (PMID 34222495, 2021). "Here we discovered that AIM2 regulated the innate immune sensors Pyrin and ZBP1 to drive inflammatory signaling and inflammatory cell death, PANoptosis, and provide host protection during infections with herpes simplex virus 1 (HSV1) and Francisella novicida." (PMID 34471287, 2021). "While RhoA-GTP was absent in WT BMDMs upon infection, it was present in Aim2–/–, Asc–/– and Casp1–/– BMDMs." (PMID 34471287, 2021). "However, IL-18 response requires both Aim2 and Nlrp3 following F. tularensis LVS as well as F. tularensis SchuS4 infections." (PMID 34690967, 2021).
infection (continued). "On the opposite, LPS-primed U937 expressing NLRP3 S806A, D, or E mutants secreted IL-1β as WT U937 in response to infection by Salmonella enterica serovar Typhimurium (SL1344 strain) and transfection with poly(dA:dT), activating the NLRC4 and AIM2 inflammasomes respectively." (PMID 34615873, 2021). "Second, we cannot exclude the possibility that the non-AIM2-dependent signaling pathway may be induced to compensate for the impaired autophagy flux, such as the NLRC4-dependent way in infection-induced autophagy or the NLRP3 inflammasome–autophagy crosstalk." (PMID 34740380, 2021). "Additionally, the AIM2 protein ASC was upregulated to 119.5% compared to mock cell cultures, while the NFκB proteins were mostly downregulated during infection." (PMID 32225009, 2020). "To investigate the potential role of an NLR/ALR that could detect Tg infection and induce apoptosis via the adaptor ASC, we used RNAi against common NLRs and AIM2." (PMID 31268602, 2019). "We observed that NLRP3 and AIM2 were recruited to the mitochondrial fraction at 6 h post infection in BMDMs, in the absence of increased expression." (PMID 30846986, 2019). "Mice lacking AIM2, ASC, or caspase-1 are highly susceptible to infection and exhibit an increased bacterial burden compared with wild-type mice." (PMID 29085810, 2017). "We observed that the pUL83/AIM2 complex was indeed formed and localized in the cytoplasm during the early stage of infection, particularly 12 h post infection, but not 24 h post infection." (PMID 28219398, 2017). "To define the inflammasome complexes that contribute to IL-1β secretion following infection with virulent IOE and regulated by MyD88, we further analyzed mRNA expression of several inflammasome complexes (NLRP3, NLRC4, AIM2) in the liver tissues of WT and MyD88-/- mice on day 7 p.i with IOE." (PMID 29049365, 2017). "Data from our previously published studies suggest that multiple inflammasome complexes including NLRP3, AIM2, and NLRC4 are upregulated during infection with virulent Ehrlichia and may play a role in the development of Ehrlichia-induced liver injury." (PMID 29049365, 2017). "AIM2 levels did not change significantly with IOE infection, and were similar between WT and MyD88-/- mice." (PMID 29049365, 2017). "To further confirm LM mainly activates NLRP3 inflammasome, we used wild-type and NLRP3−/− B6 cells to analyze the IL-1β release and caspase-1 activation upon LM infection (ATP and poly (dA:dT) were used as the NLRP3 and AIM2 inflammasome activators, respectively)." (PMID 26911557, 2016). "Unlike Nlrp3-deficient mice, Aim2-/-, Caspase-1/11-/-, Asc-/-, and IL-1R-/- mice died within 8–11 dpi after lethal Ft LVS infection or between 6 and 7 dpi after SchuS4." (PMID 27926940, 2016). "In contrast to avirulent Francisella novicida (Fn), infection with virulent Francisella tularensis ssp tularensis does not trigger activation of the host AIM2 inflammasome." (PMID 25191316, 2014). "During the course of Mtb ex vivo infections of macrophages and dendritic cells no AIM2-inflammasome activation is detected." (PMID 24130966, 2013). "Macrophages infected with mutants lacking sdhA gene trigger Aim2-dependent activation of caspase-1, secretion of IL-1β and pyroptosis, which is reversible by infection with genetically complemented bacteria." (PMID 24324933, 2013). "Indeed, mice lacking both AIM2 and NLRP3 were highly susceptible to infection and failed to control hyphal growth compared to either WT animals or rodents lacking a single inflammasome." (PMID 41249509, 2025). "Furthermore, robust phosphorylation of the necroptotic molecules MLKL and RIPK3 did not occur in Aim2–/– pBMDMs upon MPXV infection." (PMID 41225161, 2025). "Additionally, there was no cleavage of apoptotic CASP8, CASP3, or CASP7 in Aim2–/– pBMDMs following MPXV infection." (PMID 41225161, 2025).
infection (continued). "Comparison with global inhibition of IL1β, the side effect of infection may not be assumed by specific inhibition of upstream component of this pathway, such as NETs and AIM2 inflammasome." (PMID 39737165, 2024). "Moreover, the AIM2 inflammasome antagonism of type I interferon signaling – crosstalk between AIM2 inflammasome and cyclic GMP-AMP synthase pathway activating type I IFN expression – has been suggested during not only pathogen infection but also sterile inflammation." (PMID 39290706, 2024). "The Western-blot analysis conducted on inflammatory pathways, namely NF-κB and MAPKs, revealed that Aim2−/− mice kidneys exhibited significantly lower levels of activation of p-IκB/IκB, p-ERK/ERK, p-JNK/JNK, and p-p38/p38 in comparison to their WT counterparts following infection." (PMID 38918243, 2024). "For example, although it was fist found that AIM2 is the only ALR that assembles into an inflammasome with ASC in response to cytosolic dsDNA, other studies found that IFI16 forms an inflammasome with ASC upon infection by certain viruses both in the nucleus and the cytosol (e.g. HIV and KSHV)." (PMID 36864667, 2023). "As expected, AIM2 deficiency sharply reduced IL-1β secretion and NLRP3 deficiency could not abolish IL-1β secretion upon infection of the mutant strain." (PMID 36128739, 2022). "Furthermore, the expression of NLRP3 and AIM2 was comparably induced by U112 and XWK4 infection." (PMID 34869331, 2021). "Furthermore, the absence of Asc, Nlrp3/Aim2 or Casp1/11 had no impact on cell death upon infection with strains of M. tuberculosis, indicating that M. tuberculosis-induced cell death is inflammasome-independent." (PMID 32111888, 2020). "However, we found that UV-irradiating the virus led to an increase in IL-18 in ΔAIM2 THP-1 cells at 24 hours post infection, suggesting that the virus has evolved other mechanisms to inhibit inflammasome activation in macrophages that are not AIM2 dependent." (PMID 32101570, 2020). "However, since VA RNAI is primarily expressed at the later time points of a lytic infection its role as a potential AIM2 inflammasome regulator has not been addressed here." (PMID 31849970, 2019). "At 3 and 6 hours post infection, MAYV induced increased expression of Casp1, Nlrp3, Aim2 and Asc." (PMID 31479495, 2019). "For example, the PYHIN family member absent in melanoma 2 (AIM2) can directly bind to its stimulus, double-stranded DNA (dsDNA), which may be present in the cytosol during infection, to form a caspase-1 containing inflammasome." (PMID 28979266, 2017). "To determine whether AIM2 accounted for the restriction of bacterial replication in the absence of caspase-1/11, we compared infection of Aim2/Casp1/11-/- with Casp1/11-/-." (PMID 28771586, 2017). "Thus, we examined whether AIM2 is critical for in vivo inflammasome activation and development of liver injury following lethal IOE infection." (PMID 29049365, 2017). "In addition, with the exception of a few studies, the roles played by Nlrp3, Aim2 or other inflammasomes during infection with Ft LVS and SchuS4 have not been investigated." (PMID 27926940, 2016). "To examine whether AIM2 can affect expression of signal components downstream of STING, we used qPCR to monitor the mRNA expression of IFN-β and IFIT1 and ELISA to test the protein expression of IFN-β in BMDMs 24h post-infection." (PMID 27409673, 2016). "During infection of its target cells, KSHV must be coming in contact with the host innate immune system’s pattern recognition receptors (PRR), such as Toll-like receptors (TLRs), RIG-I-like receptors (RLRs), NOD-like receptors (NLRs) and absent in melanoma 2 (AIM2)-like receptors (ALRs)." (PMID 26134128, 2015).
infection (continued). "This discrepancy may be due to the fact that KSHV may be undergoing abortive infection in the PMA stimulated cells as has been shown for HSV-1 in these cells and DNA released from the lysosomes is probably recognized by AIM2, c-GAS, and others to stimulate the IL-1β and interferon responses." (PMID 26134128, 2015). "After F. novicida escapes the phagosome and replicates in the cytosol of macrophages, it is recognized by the AIM2 inflammasome complex which is essential for controlling F. novicida infection in vivo since mice lacking AIM2, ASC, or caspase-1 are highly susceptible to infection." (PMID 21698237, 2011). "Additionally, increased expression of inflammasome-related markers like Absent In Melanoma 2 (AIM2), NLR Family Pyrin Domain Containing 3 (NLRP3), and GSDMD in monocyte-macrophages suggested a higher incidence of pyroptosis during severe SARS-CoV-2 compared to moderate infection." (PMID 39928675, 2025). "Furthermore, BHRF1 is also transiently expressed during primary EBV infection, and AIM2 is upregulated after infection; a similar BHRF1-AIM2 interaction and AIM2 inflammasome activation might occur during early EBV de novo infection and play important roles in immune and inflammatory responses." (PMID 40982560, 2025). "Further, they support the hypothesis that replication competent HSV-1 is capable of decreasing both AIM2 and NLRP3 dependent inflammasome activation because UV irradiating the virus led to significant increases in IL-18 release in both the ΔAIM2 and ΔNLRP3 lines at 24 hours post-infection." (PMID 32101570, 2020). "In addition, uncontrolled cellular damage results in the release of self-DNA, which then may be sensed by AIM2 to assemble the inflammasome complex in the absence of infection, contributing to sterile inflammatory conditions." (PMID 32906750, 2020). "In conclusion, our results suggest that sirolimus suppresses NLRP3 inflammasome, which is correlated with inhibited NF-κB activation and ROS production, and induced autophagy after pH1N1 infection; however, it is not clear whether other inflammasomes, such as AIM2, are also inhibited." (PMID 30422993, 2018). "To determine if HSV-1 replication in macrophages results in inhibition of any non-AIM2 inflammasome proteins, we tested HSV-1/UV infection of the THP-1 cells lacking AIM2 and NLRP3 and compared them to WT THP-1 cells." (PMID 32101570, 2020). "Previous reports showed that infection with VZV, another alphaherpes virus, activated NLRP3 inflammasome independent of AIM2 protein." (PMID 31367214, 2019). "Infection performed in macrophages derived from Nlrp3–/–, Aim2–/–, Asc–/–and Casp1/11–/–mice indicate that the NLRP3, but not AIM2 inflammasome is essential for production of inflammatory cytokines, such as IL-1β." (PMID 31479495, 2019). "After intratracheal infection with this pathogen, CFU counts in lungs and/or BALF were higher in mice lacking caspase-1, AIM2 or NLRP3 compared to C57BL/6 controls." (PMID 30456207, 2018). "In the current study, we did not detect significant differences in the level of AIM2 mRNA expression between IOE-infected WT and MyD88-/- mice at late stages of infection (day 7 p.i.)." (PMID 29049365, 2017). "Consistent with regulation of the Aim2 inflammasome by POP2, IL-1β production by POP2 transgenic J774A.1 cells was reduced after infection with F. novicida and L. monocytogenes, but not after Salmonella Typhimurium infection." (PMID 28580947, 2017). "In the absence of Nlrp3 or Aim2, the macrophage IL-18 response to Ft LVS or SchuS4 infection was reduced by about 50%." (PMID 27926940, 2016). "However, in Aim2–/– pBMDMs, there was a complete absence of activation of pyroptotic molecules, including CASP1 and gasdermin D (GSDMD), upon MPXV infection." (PMID 41225161, 2025).
infection (continued). "In contrast, treatment with the synthetic AIM2 inflammasome ligand poly(dA:dT) did not inhibit RhoA-GTP activity in any of the genotypes tested, suggesting that infection has a distinct ability to integrate the AIM2-mediated signaling and RhoA signaling cascades to influence Pyrin activation." (PMID 34471287, 2021). "In addition, S. aureus craniotomy infection was also ASC-independent, which differs from brain abscesses that required ASC via activation of the upstream NLR sensor absent in melanoma 2 (AIM2)." (PMID 32290861, 2020). "However, excluding a significant, but seemingly unnecessary increase in IL-17 levels at day 1 post-infection in Nlrp3-/- mice, differences in the level of KC or MCP-1 that might impact myeloid cell recruitment were not discernable between Nlrp3-/-, Asc-/-, Casp1/11-/- and Aim2-/- mice." (PMID 27926940, 2016).